PXN (paxillin)
Description:
Cytoskeletal protein involved in actin-membrane attachment at sites of cell adhesion to the extracellular matrix (focal adhesion). Recruits other proteins such as TRIM15 to focal adhesion.
Tractability: Small molecule: a structure with a bound ligand is known. Antibody: its Gene Ontology location is reachable by antibodies, with high confidence. PROTAC: ubiquitination databases record sites on it; its protein half-life has been measured.
Target class: Adhesion
Gene: Protein-coding gene on chromosome 12 (120,210,439 to 120,265,795, reverse strand). Ensembl gene ENSG00000089159.
Subcellular location: Cytoplasm, cytoskeleton; Cell junction, focal adhesion; Cytoplasm, cell cortex
Subcellular location (Human Protein Atlas): Focal adhesion sites; Centrosome; Cytosol
Pathways (Reactome):
Signal Transduction: GAB1 signalosome; PTK6 Regulates RHO GTPases, RAS GTPase and MAP kinases; VEGFA-VEGFR2 Pathway
Cell-Cell communication: Localization of the PINCH-ILK-PARVIN complex to focal adhesions; Regulation of cytoskeletal remodeling and cell spreading by IPP complex components
Developmental Biology: Regulation of MITF-M-dependent genes involved in extracellular matrix, focal adhesion and epithelial-to-mesenchymal transition
Muscle contraction: Smooth Muscle Contraction
Gene Ontology:
Molecular function: beta-catenin binding; neuropilin binding; protein binding; protein phosphatase binding; vinculin binding
Biological process: cell migration; cellular response to reactive oxygen species; endothelial cell migration; growth hormone receptor signaling pathway; positive regulation of stress fiber assembly; transforming growth factor beta receptor signaling pathway; cell adhesion; signal complex assembly; signal transduction; substrate adhesion-dependent cell spreading
Cellular component: cell-cell junction; cytosol; focal adhesion; lamellipodium; plasma membrane; stress fiber; microtubule associated complex; cell cortex; cytoskeleton
Genetic constraint (gnomAD): Loss-of-function variants: 59 observed, 88.47 expected, observed/expected ratio (o/e) 0.67, 90% interval 0.54 to 0.83. The upper end of that interval is the gene's LOEUF score, 0.83, which puts it in group 3 of 6, group 1 being the genes least tolerant of losing a copy. Missense variants: 1,255 observed, 1,353.4 expected, observed/expected ratio (o/e) 0.93, 90% interval 0.88 to 0.97. Synonymous variants: 552 observed, 557.76 expected, observed/expected ratio (o/e) 0.99, 90% interval 0.92 to 1.06.
Homologues: Orthologues: chimpanzee PXN (99% identical), macaque PXN (96% identical), rabbit PXN (83% identical), dog PXN (82% identical), pig PXN (81% identical), rat Pxn (77% identical), mouse Pxn (75% identical), guinea pig PXN (51% identical), tropical clawed frog pxn (42% identical), zebrafish pxna (37% identical), zebrafish pxnb (36% identical), Drosophila melanogaster Pax (26% identical), and 7 more. Paralogues in human: TGFB1I1 (22% identical), LPXN (21% identical).
Diseases named in the same sentence as PXN in open-access papers:
PXN is named in the same sentence as 160 diseases in open-access papers, as found by Europe PMC text mining. Sharing a sentence is not in itself a finding about the gene and the disease. The quoted sentences say what the papers report.
breast carcinoma (109 papers, 2007 to 2026). "Here, we found that paxillin overexpression in breast cancer tissue is associated with a patient’s poor prognosis." (PMID 37958964, 2023). "To investigate the role of paxillin in the migration and invasion of breast cancer cells, we conducted a loss-of-function experiment." (PMID 37958964, 2023). "Bioinformatics analyses revealed that all six top canonical pathways, including the signallings of Actin cytoskeleton, ILK, VEGF, BAG2, Integrin, and Paxillin, are associated with the migration of breast cancer cells." (PMID 34571787, 2021). "Another study done on tumor samples from primary breast carcinoma showed a presence of paxillin, which is associated with upregulation of HER2." (PMID 31269666, 2019). "We previously demonstrated that MEKK2 associates with paxillin in invasive breast cancer cells, and paxillin knockdown in HEK293T cells reduced MEKK2 activity, suggesting that paxillin binds MEKK2 in multiple cell types." (PMID 27096002, 2015). "Interestingly, mammalian PKD1 is associated with the F-actin binding proteins cortactin and paxillin in invasive breast cancer cells where it may regulate cell adhesion and motility." (PMID 17592635, 2007). "Previous studies have shown that LH/FSH signaling through LHR/FSHR activates G protein-coupled ROCK–moesin and FAK–paxillin axes, significantly enhancing invasive pseudopod formation and transendothelial migration in breast cancer cells." (PMID 40431589, 2025). "Inhibition of autophagy can regulate the interaction between LC3 and paxillin, promote the formation of cell-cell focal adhesion (FA), and thus inhibit the invasion and metastasis of breast cancer, lung cancer, and liver cancer cells." (PMID 38135696, 2024). "Paxillin: Abnormal expression of paxillin has been noted across a spectrum of human malignancies, including melanoma, breast cancers, gastric cancers, and colorectal cancers." (PMID 38500921, 2024). "In the human osteosarcoma cell line, high expression of gangliosides GD3 and GD2 was reported to correlate with increased phosphorylation of breast cancer anti-estrogen resistance protein 1, paxillin, and focal adhesion kinase (FAK)." (PMID 39063133, 2024). "HGF stimulates cell migration in breast cancer cells and oleocanthal attenuates this effect by suppressing the phosphorylation of Brk, paxillin, Rac1, and c-Met." (PMID 39203892, 2024). "FCW393 reduced integrin sialylation in breast cancer and melanoma cells dose-dependently and downregulated proteins associated with the integrin-regulated FAK/paxillin and GEF/Rho/ROCK pathways, and with the VEGF-regulated Akt/NFκB/HIF-1α pathway." (PMID 38673867, 2024). "The potent tumor drug delivery ability of D/PSP@CQ/CaP can reduce the degradation of paxillin through autophagy inhibition to inhibit the autophagy-dependent breakdown of focal adhesions, thereby reducing the metastatic and growth ability of breast cancer." (PMID 37175948, 2023). "Recently, a study demonstrated the essential role of paxillin in promoting breast tumor collective cell invasion in breast cancer metastasis." (PMID 37958964, 2023). "Then, the downregulation of paxillin expression regulates Src/FAK/STAT3 to inhibit angiogenesis in estrogen-receptor-positive (ER+) breast cancer." (PMID 37175948, 2023). "The phosphorylation of paxillin at Tyr31 by Fyn plays a pivotal role in driving the migration and invasion of breast cancer cells." (PMID 37958964, 2023). "Here, we further elucidated the physiological significance of Fyn binding to paxillin, which is to directly phosphorylate paxillin Tyr31, thereby regulating actin stress fiber formation and participating in the migration and invasion of breast cancer cells." (PMID 37958964, 2023). "In this study, we provide the initial evidence that Fyn directly mediates paxillin Tyr31 phosphorylation, promoting breast cancer cell migration." (PMID 37958964, 2023).
breast carcinoma (continued). "To examine the correlation between paxillin and a patient’s prognosis, we assessed the paxillin expression in clinical samples from 91 breast cancer patients." (PMID 37958964, 2023). "We then examined the effect of paxillin Y31F overexpression on the migration and invasion of breast cancer cells." (PMID 37958964, 2023). "In the present study, we investigated the role of paxillin Tyr31 phosphorylation in the migration and invasion of breast cancer cells." (PMID 37958964, 2023). "Our study showed that paxillin Tyr31 phosphorylation plays an important role in the migration and invasion of breast cancer cells." (PMID 37958964, 2023). "For example, magnolol can inhibit the expression of lysyl oxidase from disrupting FAK/Src/paxillin signaling to inhibit the migration and invasion of breast cancer cells, which is considered to be an ideal strategy for breast cancer treatment." (PMID 37175948, 2023). "Recent studies have further shown that mifepristone can inhibit the formation of the FAK/Src/paxillin complex to reduce the potential of breast cancer cell migration and adhesion." (PMID 37175948, 2023). "Functional links between PXN and tumorigenesis such as renal cell carcinoma, breast cancer, and glioblastoma have been revealed." (PMID 36923874, 2023). "Our findings suggest that paxillin Tyr31 phosphorylation mediated by Fyn plays an important role in the migration and invasion of breast cancer cells by participating in the formation of actin stress fibers." (PMID 37958964, 2023). "The cargo receptor c-Cbl targets the autophagosome for the degradation of paxillin phosphorylated at the Y118 residue, triggering FA breakdown, thereby regulating cell–matrix adhesion turnover and cell motility in breast cancer cells." (PMID 37175948, 2023). "Retinoic acid can dissociate phosphorylated paxillin from FA to the nucleus to translocate and inhibit the formation of FA complex, which inhibits the adhesion and migration of breast cancer cells." (PMID 37175948, 2023). "Growing evidence has shown that paxillin is aberrantly expressed in a variety of human malignancies, such as melanoma, breast cancers, gastric cancers, and colorectal cancers." (PMID 37175948, 2023). "Oleanolic acid derivatives can downregulate the expression of integrin β1/FAK/paxillin by reducing the level of β1 integrin, thereby inhibiting the invasion and migration of breast cancer cells." (PMID 37175948, 2023). "In summary, our study provides important new insights into the role of Fyn in governing paxillin activity during breast cancer cell migration." (PMID 37958964, 2023). "Immunoidentification of focal adhesion (FA) proteins showed alterations in Tyr397FAK, FAK, and paxillin protein levels, which indicated their role in the response of breast cancer cells to the studied compounds." (PMID 36982173, 2023). "A further study using chloroquine (CQ) treatment in breast cancer models demonstrated a reduced rate of paxillin degradation both in vitro and in vivo." (PMID 35884592, 2022). "In the MDA-MB-231 breast cancer cell line, CuE (0.2 μM, 1–6 h) reduced focal adhesions (i.e., through paxillin staining) and polymerized actin (i.e., through phalloidin staining)." (PMID 36355554, 2022). "Human breast cancer cells treated with salvicine showed lower levels of genes for integrin a3, integrin a6, integration E, integrin b3, integrin b5, integrin b8, paxillin, and FAK." (PMID 35719997, 2022). "We had previously reported that the administration of 1 μM RA for short periods (20 min) increased the activation/phosphorylation of FAK and Paxillin, inducing their nuclear relocalization in T-47D breast cancer cells." (PMID 36230951, 2022). "As a scaffolding protein, paxillin has been shown to control the signalling of estrogen to induce PI3K complex signalling to support breast cancer cell attachment, migration, and invasion." (PMID 34571787, 2021).
breast carcinoma (continued). "And MLK3 promoted migration and invasion of breast cancer cells through regulating the phosphorylation of paxillin." (PMID 34268882, 2021). "The FAK/Src/paxillin and RhoA/ROCK1 signaling pathways were also implicated in the migration of breast cancer cells mediated by a cytoskeletal protein with a prominent GTPase activity named SEPT9 isoform 1 protein (SEPT9_i1)." (PMID 33562737, 2021). "Previous studies have demonstrated that PXN plays key roles in multiple receptor-activated signaling pathways in breast cancer metastasis, taking part in cell transformation and migration." (PMID 34135128, 2021). "Our previous work, in breast cancer, reported that depletion of RhoU expression led to increased peripheral adhesions and reduced paxillin S272 phosphorylation; the same phenotype observed here in FASN knockdown cells." (PMID 32139877, 2020). "More recently, DLX6-AS1 (a long noncoding RNA that adsorbs miRNA-199b) promoted epithelial–mesenchymal transition and cisplatin resistance via the miR-199b-5p/PXN axis in breast cancer cells." (PMID 33322675, 2020). "In this study, we first examined the correlation of SEPT9 with clinical characteristics and paxillin in breast cancer samples." (PMID 31558699, 2019). "Our results showed that SEPT9 and paxillin were overexpressed in 74.5% (41/55) and 54.5% (30/55) of the primary breast cancer clinical samples, respectively." (PMID 31558699, 2019). "Some of the essential molecules, which are critically involved in breast cancer, are catenins, actinin, talin, vinculin, and paxillin." (PMID 31269666, 2019). "As shown in earlier studies, in breast tumors, PXN is overexpressed and regulates breast cancer cell metastasis." (PMID 31269666, 2019). "We also found that reducing PXN levels restores both focal adhesion morphology and motility, confirming the results in mammary cancer." (PMID 30200999, 2018). "In this work, we evaluated the ability of nobiletin to inhibit tumor angiogenesis by regulating Src/FAK/STAT3 signaling through PXN in ER+ breast cancer cells." (PMID 28468300, 2017). "Together, these results provide novel insights into the requirement of phospho-site specific post-translational mechanism of paxillin for autophagy targeting to regulate cell-matrix adhesion turnover and cell locomotion in breast cancer cells." (PMID 28415719, 2017). "In conclusion, nobiletin inhibited tumor angiogenesis by regulating Src/FAK/STAT3-mediated signaling through PXN in ER+ breast cancer cells." (PMID 28468300, 2017). "Nobiletin inhibited tumor angiogenesis by regulating Src, FAK, and STAT3 signaling through PXN in ER+ breast cancer cells." (PMID 28468300, 2017). "Particularly, paxillin has been shown to control the signaling of estrogen (17-β estradiol) to FAK/N-WASP/Arp2/3 complex in breast cancer cells." (PMID 28214467, 2017). "LIMK1 overexpression has been noted in breast cancer progression, while paxillin overexpression has been shown to enhance breast cancer metastasis." (PMID 27769065, 2016). "Paxillin and Hic-5 play a critical role in breast cancer cell morphology and plasticity during invasion." (PMID 26980710, 2016). "In vitro studies concerning paxillin function during breast cancer lung metastasis identified paxillin as a key regulator of 3D adhesion assembly, stabilization and disassembly." (PMID 25955236, 2015). "That LOX was expressed in 79% of human breast cancers revealed the attenuated metastasis of human breast cancer cells by a downregulation of adhesion kinase and the paxillin-signaling pathway." (PMID 24885752, 2014). "Previous studies have demonstrated that paxillin was overexpressed in esophageal squamous cell carcinoma, lung carcinoma, breast cancer and prostate cancer." (PMID 24348846, 2014). "For instance, in breast cancer, cell migration and invasion stimulated by breast tumor kinase (Brk) is mediated through PXN phosphorylation, PXN is the substrate of Brk and functions as a “platform” of Brk." (PMID 24180516, 2013).
breast carcinoma (continued). "Paxillin (PXN) is vital to drive the assembly of focal adhesion and its disruption could reduce breast cancer cell migration." (PMID 40731028, 2025). "A study relating Sgsm2 with breast cancer showed that silencing the expression of Sgsm2 protein resulted in a decreased expression of epithelial markers such as E-cadherin, β-catenin, and Paxillin, in addition to increased expression of markers such as Snail and Twist-1." (PMID 39895822, 2024). "In the present study, we sought to understand the mechanism by which paxillin is involved in the migration and invasion of breast cancer cells and to determine the critical role of paxillin Tyr31 phosphorylation on the migration and invasion of breast cancer cells." (PMID 37958964, 2023). "Based on these reports, we speculate that paxillin Tyr31 phosphorylation is involved in the actin stress fiber formation through the TGF-β1/Fyn/paxillin/Rho-kinase signaling pathway, thereby leading to the migration and invasion of breast cancer cells." (PMID 37958964, 2023). "Our results showed that paxillin Y31F overexpression inhibited the TGF-β1-induced migration and invasion of both MDA-MB-231 and MCF7 cells, suggesting that paxillin Tyr31 phosphorylation plays an important role in the migration and invasion of breast cancer cells." (PMID 37958964, 2023). "Furthermore, a recent study suggested the involvement of the Fyn/paxillin signaling pathway in breast cancer cell migration." (PMID 37958964, 2023). "Paxillin knockdown inhibited the migration and invasion of breast cancer cells." (PMID 37958964, 2023). "Paxillin Tyr31 phosphorylation could be a potential target site for the treatment of breast cancer metastasis." (PMID 37958964, 2023). "However, the specific impact of the distinct tyrosine phosphorylation events of paxillin in the progression of breast cancer remains to be fully elucidated." (PMID 37958964, 2023). "Additionally, the mRNA and protein levels of paxillin were also higher in high metastatic potential human breast cancer cells than in low metastatic potential cells." (PMID 37175948, 2023). "We provide evidence that paxillin Tyr31 phosphorylation is involved in the migration and invasion of breast cancer cells, suggesting that paxillin Tyr31 phosphorylation could be a potential therapeutic target for mitigating breast cancer metastasis." (PMID 37958964, 2023). "As a derivative of 3,4-methylenedioxy-β-nitrostyrene, HPW-RX40 can not only inhibit integrin from preventing platelet aggregation but also inhibit the activation of the integrin β1/FAK/paxillin signaling pathway from enhancing the sensitivity of breast cancer cells to anoikis." (PMID 37175948, 2023). "Previous research indicates that Y118-Paxillin phosphorylation levels are inversely correlated with cancer metastasis in breast cancer patient tissue samples, suggesting that, similar to our findings, Y118-Paxillin phosphorylation does not correlate with an invasive phenotype." (PMID 36723624, 2023). "Additionally, a recent study demonstrated that hesperetin inhibits the migration and invasion of breast cancer cells by suppressing the phosphorylation of paxillin at Tyr31, Tyr88, and Tyr118." (PMID 37958964, 2023). "Other significant pathways included pathways implicated in breast cancer, among them: actin cytoskeleton, the role of BRCA1 in DNA damage response, paxillin, UVA-induced MAPK, aryl hydrocarbon receptor, ILK, and the molecular mechanisms of cancer-signaling pathways." (PMID 36360779, 2022). "Moreover, Ph (10–150 μM, 24 h) reduced mediators involved in the cytoskeletal organization, including p-FAK, paxillin, and alpha-smooth muscle actin in the breast cancer MDA-MB-231 cell line." (PMID 36355554, 2022). "In addition to DRP1, cofilin is also translocated to mitochondrial outer membrane in breast cancer cells; however, it is unclear if paxillin is translocated to mitochondria in response to LPS." (PMID 34475475, 2021).